BMI1 (BMI1 proto-oncogene, polycomb ring finger)
Diseases named in the same sentence as BMI1 in open-access papers (continued):
Sharing a sentence is not in itself a finding about the gene and the disease.
cancer (continued). "In addition to its role in tumorigenesis and tumor progression, Bmi-1 also plays an important part in self-renewal of hematopoietic stem cells, neural stem cells, mammary stem cells, and CSCs in some cancers." (PMID 27009837, 2016). "Importantly, aberrant BMI1 expression has been found in premalignant gastrointestinal lesions, which points to its possible role in cancer initiation." (PMID 27846243, 2016). "Bmi-1 is also required for maintenance of stemness in several cancers." (PMID 26847520, 2016). "In this study, we employed lineage tracing to show that Bmi1-expressing cells mark a distinct, largely luminal castration-resistant prostate epithelial cell population that is capable of prostate regeneration and cancer initiation." (PMID 27703144, 2016). "In addition, stemness factors including Nanog, Sox2, Oct4, and Bmi1 are highly expressed in cancer cells and have cancer stem cell properties." (PMID 27189061, 2016). "miR-218 inhibits glioma cancer stem cells by targeting BMI1." (PMID 26349457, 2016). "Moreover, Bmi1 has been reported to confer anti-apoptotic ability and chemoresistance to cancer cells." (PMID 27177084, 2016). "Likewise, BMI1 plays a critical role in the self-renewal of prostate and lung stem cells, and thus makes an essential contribution to their cancer stem cells." (PMID 26633535, 2015). "What is unknown, however, is whether the specific localization of BMI1 as cytoplasmic versus nuclear significantly influences the development or progression of OSA as has been shown in other cancers." (PMID 26110620, 2015). "This suppression thus plays a major role in BMI1-mediated maintenance of the self-renewal of hematopoietic stem cells (HSCs), neural stem cells (NSCs), stem cells of other tissues, and most importantly, cancer stem cells (CSC)." (PMID 26425649, 2015). "This feedback loop regulating BMI1/COX4i1 expression may be relevant in promoting cancer and maintaining stem cell phenotype." (PMID 25726526, 2015). "A recent report has suggested that Bmi1 mediates OTSCC progression through cancer stem cells." (PMID 25915207, 2015). "Specifically, through ubiquitination of H2A and γH2AX, BMI1 enhances homologous recombination (HR)-mediated repair of double-stranded breaks (DSBs), an activity that sustains cancer survival during genotoxic agents-based therapies, thereby contributing to BMI1's ability in promoting tumorigenesis." (PMID 26425649, 2015). "In addition, we further investigated the colocalization between ALDH1A1 and several cancer stem/progenitor markers (EpCAM, BMI1, CD13, CD24, CD90 and CD133) which have discovered recently to evaluate “stemness” in ALDH1A1-overexpressing cells in this report." (PMID 26160842, 2015). "Importantly, BORIS-silencing led to down-regulation of hTERT, stem cell (NANOG, OCT4, SOX2 and BMI1) and cancer stem cell markers (ABCG2, CD44 and ALDH1) genes." (PMID 26185996, 2015). "Next, we asked whether the changes in cluster formation and in cell migration/wound healing upon BMI1 downregulation could be influenced by the Ink4a-mediated cell cycle control exerted by BMI1 in various physiological and cancer-related contexts." (PMID 24460684, 2014). "Thus, understanding the molecular mechanisms by which Bmi1 regulates the stem cell properties of cancer cells is likely to pave the way for newer therapeutic modules." (PMID 25348805, 2014). "Bmi1 belongs to the Polycomb Group (PcG) gene family of proteins that function as chromatin modifiers and play important roles in stem cell maintenance as well as cancer development." (PMID 25348805, 2014). "Preclinical and clinical evidences suggested that Bmi1 mediates chemoresistance in various cancers." (PMID 25348805, 2014). "The Bmi1 polycomb ring finger oncogene, a transcriptional repressor belonging to the Polycomb group of proteins plays an important role in the regulation of stem cell self-renewal and is elevated in several cancers." (PMID 25348805, 2014).
cancer (continued). "Nevertheless, more attention should be paid to the discovery that ERα regulated expression of Bmi1, which could be a challenge to the general opinion of Bmi1 for its crucial role in regulating self-renewal of stem cells or cancer stem cells." (PMID 24559156, 2014). "BMI1 overexpression is observed in numerous human cancers, including MB." (PMID 24460684, 2014). "Interestingly, BMI-1, the mammalian homolog of Psc, is a known oncogene whose upregulation correlates with poor prognosis in a number of cancers." (PMID 23893745, 2013). "To determine whether the expression of Bmi1 in cancer cells correlates with the levels of TAMs, we examined Bmi1, CD68, and CD163 expression in gastrointestinal cancer tissues using IHC." (PMID 24312366, 2013). "B cell-specific moloney murine leukemia virus integration site 1 (BMI1) is a transcriptional repressor of polycomb repressive complex 1, which is involved in the proliferation, senescence, migration, and tumorigenesis of cancer." (PMID 23820733, 2013). "To explore the regulation of Bmi1 expression in cancer cells, we examined a possible correlation between Bmi1 expression in gastrointestinal cancer cells and infiltrating macrophages in the tumor microenvironment, and investigated the mechanism underlying the regulation of Bmi1 expression." (PMID 24312366, 2013). "Recent studies also implicate Bmi1 as a crucial protein for the maintenance and self-renewal of normal stem cells, including hematopoietic, neural, myeloid and squamous stem cells as well as cancer stem cells in several tumor types." (PMID 23437065, 2013). "Furthermore, we compared miR-30e* expression levels between high and low Bmi1 expressing cancer tissues." (PMID 24312366, 2013). "The box plots of the data for BMI1 protein expression in stroma exhibited a wide inter-specimen variation in cancer specimens, compared with normal tissues and revealed a significant difference in the level of protein between normal and CaP tissues (p<0.05, Fig. 1Bii)." (PMID 23308129, 2013). "Increased expression of Bmi1 mRNA was observed in this screening and follow-up experiments indicate that Bmi1 appears to be a functional component of hTERT- or E6-mediated cell immortalization and that its expression further increases during cancer progression." (PMID 23592995, 2013). "Bmi1 is overexpressed in a variety of human cancers including gastrointestinal cancer." (PMID 24312366, 2013). "In addition, BMI-1 knockdown in mouse models suppresses malignant tumour formation, indicating a requirement for BMI-1 to sustain cancer stem cell renewal." (PMID 22771539, 2013). "However, it was also well known that BMI1 modulated the DDR pathway and PI3K/AKT pathway that then caused cancer cell progression." (PMID 23820733, 2013). "In support of this hypothesis, previous analysis of the SALL4/Bmi-1 regulatory pathway in cancer stem cells revealed the potential of this pathway as an attractive target for therapeutic intervention." (PMID 23363002, 2013). "All eight cancers with Gli-1-positive nuclei expressed BMI1." (PMID 23046527, 2012). "The polycomb group (PcG) family BMI1, acting downstream of the hedgehog (Hh) pathway, plays an essential role in the self-renewal of haematopoietic, neural, and intestinal stem cells, and is dysregulated in many types of cancer." (PMID 23046527, 2012). "Moreover, various studies have revealed that Bmi-1 is required for the maintenance of the self-renewing proliferation of several normal and cancer stem cells, including neural crest stem cells and mammary stem cells." (PMID 22967049, 2012). "High Bmi-1 expression was identified in all histologic types from squamous epithelium to carcinoma." (PMID 23078618, 2012).
cancer (continued). "However, as many as 72.2% (182 of 252) of the cancer tissues were defined as manifesting high Bmi-1 expression." (PMID 21276221, 2011). "BMI-1 is thought to mediate cell invasion in several types of cancer." (PMID 21851624, 2011). "It has been demonstrated that over-expression of BMI-1 occurs in a variety of cancers, including several types of leukemia and solid tumors such as non–small cell lung cancer, mantle cell lymphomas, colorectal cancer and prostate cancer suggesting a role in tumor cell growth and survival." (PMID 22132147, 2011). "Also the increased expressionof Bmi-1 was one of the key regulatory factors determining a cellular phenotypecaptured by the expression of a death-from-cancer signature in a broad spectrum oftherapy-resistant clinically lethal malignancies." (PMID 21445297, 2011). "In the present study we have analyzed levels of Mel-18 and Bmi-1 in normal breast tissue samples from patients operated for cancer, and compared to breast tissue samples from patients operated for non malignant condition and with no previously history of malignant disease." (PMID 21162745, 2010). "In addition to its role in cancer, BMI1 is also known to be required for self-renewal of neural, hematopoietic, intestinal and mammary stem cells." (PMID 20569464, 2010). "INK4A/ARF tumor suppressor locus is one of the most important cancer relevant targets of Bmi-1." (PMID 20723236, 2010). "In view of the well established roles of BMI1 in oncogenesis and stem cell maintenance, our studies have important implications for the pathobiology of cancer and the development of novel treatment strategies for cancer patients." (PMID 20569464, 2010). "Furthermore, Bmi-1 expression has been identified as a prognostic factor only in certain types of cancer." (PMID 20145620, 2010). "This may be attributed to higher expression of Bmi-1 in cancer cells from later stage tumor tissue than from early stage tumor tissue." (PMID 20809956, 2010). "Because BMI1 is an important regulator of cell proliferation and stem cell phenotype, its own regulators are likely to be very important for onocogenesis and self-renewal of normal and cancer stem cells." (PMID 20170541, 2010). "Although INK4A/ARF locus is the most cancer relevant target of BMI1 and Mel-18, there are several new reports, which suggest that these PcG proteins, in particular BMI1 may regulate tumorigenesis independent of p16 pathway." (PMID 20170541, 2010). "In support of this hypothesis, we used an in vitro cell migration model to measure the effect of Mel-18 and BMI1 on cell migration, which is one of the important steps in cancer metastasis." (PMID 20170541, 2010). "Because expression of Mel-18 or BMI1 correlated with lymph node metastasis, we hypothesized that these PcG proteins may regulate cancer metastasis." (PMID 20170541, 2010). "Moreover, developmental signaling pathways, such as Notch and Hedgehog, as well as the polycomb gene BMI1 are thought to regulate both normal and cancer stem cells." (PMID 20824134, 2010). "Mel-18 and BMI1 may regulate tumorigenesis, cell migration and cancer metastasis via both p16- and AKT-dependent growth regulatory pathways." (PMID 20170541, 2010). "It was reported that MEL18 could repress BMI1 in cancer cells and knockdown one of PcGs might release other PcGs from its target gene (such as p16)." (PMID 21060834, 2010). "Bmi-1 is one of the best known PcG gene, which was initially identified for its ability to cooperate with c-Myc in lymphomagenesis and subsequently was found to be overexpressed in many kinds of human cancers and thus was accepted as an oncogene." (PMID 20723236, 2010). "Our results also suggest that the PS domain of BMI1 could be targeted for the treatment of proliferative disorders such as cancer and aging." (PMID 20569464, 2010).
cancer (continued). "Interestingly, Bmi-1 overexpression has been earlier reported to be constantly present in a small series of patients (N=10) with oral dysplastic and carcinoma tissue, but our research data consisted of 73 patients." (PMID 20145620, 2010). "Additionally, while BMI1 promotes tumorigenesis in a variety of human cancers, PTEN potently suppresses tumorigenesis." (PMID 19903340, 2009). "This death may be related to a pro-malignant function of Bmi1, as indeed it was reported that silencing of the Bmi1 expression promotes cancer-specific cell death." (PMID 19956605, 2009). "However, Mel-18 and Bmi-1 have both been shown to increase proliferation and survival of cancer cells." (PMID 19333393, 2009). "As PTEN is inactivated in human cancers, loss of PTEN function may release its inhibition on BMI1 during tumorigenesis." (PMID 19903340, 2009). "Screening of several key proteins controlling cell cycle, development, metabolism, apoptosis and growth, including Erk, Akt, GSK3β, p16 and p14, Bcl-2, c-Myc, Nestin and Sox2, showed that downregulation of Bmi1 reduced GSK3β protein levels and induced differentiation in cancer cells." (PMID 19823589, 2009). "Moreover, silencing of Bmi1 by siRNA leads to the death of cancer cells specifically, suggesting that its activity is also essential for viability during the malignant stage." (PMID 19956605, 2009). "Bmi1 was first identified as an oncogene inducing B and T cell leukemias and later it has been repeatedly shown to be highly overexpressed in various cancer cell-lines and tumors." (PMID 19956605, 2009). "The role of Bmi1 in adult stem cells, combined with its frequent overexpression in cancer, has led to the theory that BMI1 might play a role in cancer stem cells (or more accurately, tumour-initiating cells)." (PMID 19099573, 2008). "The transcription factors Oct-3/4 and BMI-1 are important for embryonic stem cell self-renewal and long-term proliferative capacity of normal haematopoetic and leukaemic stem cells, and are expressed in cancer stem-like cells." (PMID 18268494, 2008). "This suggests that other BMI-1 cooperative factors may be involved in the BMI-1-dependent cancer-specific growth retardation." (PMID 18475299, 2008). "The differential effect of Bmi-1 knockdown in the normal and cancer cells may be beneficial if Bmi-1 were to be targeted for anticancer therapy." (PMID 17179983, 2007). "In particular, Bmi-1 overexpression is detected in several types of human cancers, leading to the hypothesis that Bmi-1 facilitates tumorigenesis by nullifying the p16INK4A-mediated extrinsic senescence pathway." (PMID 17179983, 2007). "We also compared the levels of Bmi-1 staining in situ in cultured normal and cancer cells." (PMID 17179983, 2007). "Consistent with recent studies demonstrating overexpression of PcG genes in cancer, we found that both BMI-1 and EZH2 are strongly expressed by a variety of tumours." (PMID 17024127, 2006). "Thus, inhibition of BMI1 could be a potential target for cancer prevention approaches and merits further consideration and additional functional studies." (PMID 41385756, 2026). "Consequently, limiting BMI1 could be a potential target for cancer prevention approaches that merits further consideration and additional functional studies." (PMID 41385756, 2026). "Moreover, Bmi-1 is expressed in almost all tissues given that it is involved in various cellular processes such as DNA damage response, senescence, cell cycle, self-renewal of stem cells, mitochondrial reactive oxygen species, and metabolism of cancer cells." (PMID 39866230, 2025). "The potential discovery of downstream effectors of Bmi-1, which could also lead to improved detection of cancers—perhaps an early application of RNAi Bmi-1 inhibition as a preventative measure in a patient identified as high risk—might hold just as much potential in developing future therapies." (PMID 39866230, 2025).
cancer (continued). "In addition, B68 induces senescence in cancer cells by targeting BMI1, which berberine cannot do." (PMID 39721027, 2025). "Bmi‐1 splicing dysregulation may result in the creation of carcinogenic protein isoforms or changes in gene expression patterns, both of which could contribute to cancer formation." (PMID 39791545, 2025). "Therefore, elucidating the functional role of Bmi-1 in CSC-mediated cancer progression may unveil an attractive target for mechanism-based, developmental therapeutics." (PMID 36726797, 2023). "Similarly, this ability has been also recently described for PTC596, suggesting that the modulation of BMI-1 might be a promising approach to curing cancer patients." (PMID 38275623, 2023). "Thus, the role of BMI-1 in invasion and metastasis may be dependent on the cancer type and its molecular context." (PMID 36497428, 2022). "Furthermore, miR-218, miR-330-3p, and miR-498 may regulate the migration and invasion of cancer cells through the Bmi-1/Akt axis." (PMID 35897796, 2022). "BMI1 is a novel target for cancer therapy and may be a valid target in AML therapy." (PMID 33540760, 2021). "Knock-down and overexpression studies in cancer cell lines suggest that Usp22 may promote cancer through the positive regulation of well-known oncogenes including BMI1, c-MYC, SIRT1, cyclin B1, and KDM1A, mainly through the regulation of cell cycle progression." (PMID 34503086, 2021). "The decrease of Bmi‐1 expression and proportion of CD44+/CD24− subpopulation cells showed the loss of stemness and that TM‐induced ER stress might result in differentiation of cancer stem cells." (PMID 34320274, 2021). "Furthermore, low BMI1 expression was found to enhance the chemosensitivity of cancer cells." (PMID 34442383, 2021). "The bioinformatics prediction and the result of luciferase assay identified that Bmi-1 was directly targeted by miR-203, which radiosensitized cancer cells through repression of Bmi-1, ectopic expression of Bmi-1 without 3′-UTR could reverse the improvement of radiosensitivity by miR-203." (PMID 32182776, 2020). "Bmi-1, the first functionally identified PcG member, is frequently dysregulated in various cancers and strongly correlates with tumor aggressiveness; thus, its presence predicts a poor prognosis, but little attention has been paid to the downstream regulatory mechanism of Bmi-1 in GC promotion." (PMID 32580736, 2020). "In addition, circ_001680 could upregulate the miR-340 target gene BMI1, promote the cancer stem cell (CSC) population of CRC cells and induce irinotecan chemotherapy resistance." (PMID 32005118, 2020). "Furthermore, we demonstrated that Bmi-1 is inversely associated with Raf kinase inhibitory protein (RKIP), a regulator of apoptosis induced by chemotherapeutic agents and a clinically relevant cancer metastasis suppressor gene." (PMID 32580736, 2020). "We asked whether toxicity associated with BMI1-inhibition could be relevant to other cancer cell types and, thus, rule out that our findings were limited to haploid cells." (PMID 32343689, 2020). "Bmi-1 may represent a promising target for the prevention and therapy of various cancer types." (PMID 32059385, 2020). "In addition, NRP2 upregulators bound with VEGFR2 and integrins can inhibit BMI1 upregulation, which may lead to suppressed cancer development." (PMID 30871059, 2019). "Finally, we discussed the mechanism that Bmi1 as the cancer stem cell self-renewal target could be applied to the combination therapy with natural compounds." (PMID 31366257, 2019). "Moreover, the expression of Bmi1, which is regulated by c-Myc26, was also decreased by Huaier n-butanol extract treatment, suggesting that the c-Myc-Bmi1 signalling pathway plays an important role in the anti-cancer effect of Huaier n-butanol extract." (PMID 30679589, 2019).